ERBB2 (erb-b2 receptor tyrosine kinase 2)
Diseases named in the same sentence as ERBB2 in open-access papers (continued):
Sharing a sentence is not in itself a finding about the gene and the disease.
breast cancer (continued). "Indeed, we observe that acetazolamide or AMB added to the bath solution abolishes the decrease in core-to-periphery pHo gradient when murine ErbB2-induced breast cancer organoids are exposed to CO2/HCO3–-containing solution." (PMID 37098526, 2023). "This axis can be identified as a “reprogramming metabolism pathway” and may be an alternative therapeutic strategy for treating ErbB2-overexpressing breast cancers." (PMID 37958341, 2023). "Breast cancer is the perfect example since RNA-based profiling tests provide clinical and biological useful information beyond individual somatic gene mutations or amplifications such as PIK3CA or ERBB2 5–8." (PMID 36859416, 2023). "Epidermal growth factor receptor 2 (ErbB2) is an important breast cancer biomarker, and both the extraction and quantification of ErbB2 can be achieved by the silicon MN electrochemical sensor simultaneously, which is of great significance for the prevention and early detection of breast cancer." (PMID 37223469, 2023). "Additionally, Tat-SP9 also showed more potent anti-proliferative efficacy than Tat-SP4 in ERBB2-POSITIVE breast cancer cells." (PMID 37958451, 2023). "In the older group, there was a significant difference in breast cancer subtype, with a decrease in patients with HR+/ERBB2– (PBC, 99 of 336 [29.46%]; CBC, 68 of 336 [20.24%]) and an increase in patients with ERBB2+ (PBC, 57 of 336 [16.96%]; CBC, 84 of 336 [25.00%]) (P = .002)." (PMID 38100108, 2023). "ERBB2 fusions were most frequently observed in breast cancer followed by gastroesophageal cancers." (PMID 37168365, 2023). "This breast cancer cell line is known to overexpress the ErbB2 protein." (PMID 38137912, 2023). "HER2 (ERBB2)-positive breast cancer accounts for ∼20% of all breast cancers." (PMID 36661191, 2023). "To mimic this, we used the ErbB2-expressing breast cancer cell line MDA-MB-453 transduced with GFP." (PMID 37885894, 2023). "Overexpression of ERBB2 occurs in 20–30% of breast cancers, often due to ERBB2 gene amplification." (PMID 37219601, 2023). "Approximately 20% of newly diagnosed breast cancers are due to the overexpression of ErbB2." (PMID 36768973, 2023). "Some breast cancer cells activate the AKT pathway induced by the heterodimer of ErbB2." (PMID 37284316, 2023). "In human breast cancer, it is known that the cancer can be classified into five molecular subtypes (Luminal A, Luminal B, Basal-like, ErbB2+, and Normal-like), and these classifications have been found to have significant associations with survival and clinical outcomes." (PMID 37859946, 2023). "Nevertheless, the combination of trastuzumab and both PPRHs against ERBB2 revealed a certain degree of synergism depending on the concentration of PPRH tested, confirming the potential applicability of such combinations as therapeutic strategies for HER-2-positive breast cancer." (PMID 37108234, 2023). "An expression trend between TFAP2 and ERBB2 in breast cancer was observed." (PMID 37291585, 2023). "This scenario could also apply to patients who know the aberrantly expressed condition gene responsible for their pathology (e.g., ERBB2/Her2 for women with Her2-dependent breast cancer)." (PMID 37305078, 2023). "Breast cancer is traditionally classified into five subtypes based on the expression levels of different receptors in breast tissue: luminal A, luminal B, overexpressor of ErbB2, basal-like, and triple-negative subtypes." (PMID 38081884, 2023). "The determination of HER2 status is of the utmost importance for breast cancer patients, for the reason of impressive improved clinical outcome of patients who received anti-ERBB2 therapies in metastatic and adjuvant settings, as well as in the neoadjuvant setting." (PMID 36698078, 2023). "Human epidermal growth factor receptor 2 (HER2) is a family of transmembrane receptor tyrosine kinases encoded by the ERBB2 gene, which has been an important area of research and treatment target in breast cancer." (PMID 37017812, 2023).
breast cancer (continued). "Likewise, HR−HER2-positive breast cancer showed more differentially mutated genes (ERBB2, PRKDC, PTEN and NEB) than HR−HER2-zero breast cancer (only SLX4) compared to HR−HER2-low breast cancer (3 vs 1)." (PMID 37264417, 2023). "However, more than 25% of early-stage ERBB2+ breast cancer patients develop resistance to trastuzumab and more than 75% late-stage ERBB2+ breast cancers are resistant to trastuzumab even if given in combination with anthracyclines." (PMID 37359373, 2023). "Hence, integrin β4 signaling was shown to promote breast cancer cell adhesion to brain microvascular endothelium through induction of ErbB2-mediated secretion of VEGF." (PMID 37173970, 2023). "This may in part be associated with patients with weak ER or strong PR expression, who were less likely to have ERBB2-low breast cancer (eFigure 2 in Supplement 1)." (PMID 36821125, 2023). "Ethanol stimulates invasion by breast cancer overexpressing ErbB2." (PMID 36310188, 2023). "The HER2-enriched subtype, accounting for approximately 15%–20% of breast cancer is characterized by high expression of the ERBB2 gene, but shows considerable heterogeneity in its presentation which may also include differences in ER+ expression (ER+/ER-)." (PMID 37662839, 2023). "For example, both tumors were mainly composed of epithelial breast cancer cells (EPCAM+) with a similar distribution of hormone receptors (ERBB2 for HER2, ESR1 for estrogen receptor, and PGR for progesterone receptor) and histology markers (CDH1 for E-cadherin)." (PMID 37301892, 2023). "In addition, MDA-MB-436 cells are HER2 (receptor tyrosine-protein kinase erbB-2), while HCC1954 cells are HER2 positive, which is associated with a more aggressive form of breast cancer." (PMID 37239845, 2023). "Additional factors associated with increased breast cancer–specific mortality were non-Hispanic Black race (HR, 1.70; 95% CI, 1.26-2.30; P < .001) and aggressive tumor subtype (ER-negative/ERBB2-negative) (HR, 2.07; 95% CI, 1.67-2.56; P < .001)." (PMID 37083666, 2023). "To evaluate the specificity of this ddPCR assay, we included a set of n = 7 HDs (to define the thresholds on ERBB2 amplification and overexpression) and EV‐RNA extracted from conditioned cultured medium of HER2+ (SKBR3) and HER2‐ (MDAMB231) breast cancer cell lines." (PMID 38046436, 2023). "This is consistent with human breast cancer CNVs, which often affect a whole chromosome arm on either side of the centromere except in the cases of strong selective pressure over a particular region, such as the cases of ERBB2 in breast cancer or AR in prostate cancer." (PMID 37805590, 2023). "There are three primary subtypes of breast cancer: triple-negative breast cancer (15%, where the tumors lack all three molecular markers), ERBB2-positive breast cancer (15–20%), and hormone-receptor-positive/human epidermal growth factor 2 (ERBB2)-negative (70% of patients) breast cancer." (PMID 37049543, 2023). "HER2 + is a breast cancer subtype defined by overexpression of the HER2 protein or ERBB2 gene." (PMID 36598637, 2023). "Breast cancer was the cancer most frequently diagnosed in the anti-ERBB2 drug group (209 [97.7%]), whereas chronic myeloid leukemia (611 [29.6%]) and BC (476 [23.1%]) were the 2 most frequent types of cancer in the other anticancer drug group (eFigure 2 in Supplement 1)." (PMID 37883083, 2023). "Likewise, the six recombinant adaptor proteins specifically bound to a panel of additional breast carcinoma, ovarian carcinoma, glioblastoma and melanoma cell lines with high or moderate ErbB2 expression." (PMID 36688995, 2023). "We previously documented a correspondingly smaller [lactate]-to-[glucose] ratio in ErbB2-induced breast carcinomas relative to carcinogen-induced breast carcinomas, which is indicative of lower fermentative glycolysis and can explain the difference in tumor acidification." (PMID 37098526, 2023).
breast cancer (continued). "In order to evaluate further the composition of the tumor microenvironment and how it is influenced by acetazolamide in mice carrying ErbB2-induced breast carcinomas, we collect blood samples and microdialysates from probes inserted into tumors and matched normal breast tissue." (PMID 37098526, 2023). "We have previously demonstrated that tumor feed arteries supplying ErbB2-induced breast carcinomas are specialized toward heightened perfusion as they have lower α1-adrenoceptor expression and show lower responsiveness to noradrenaline and electrical field stimulation of sympathetic nerve endings." (PMID 37098526, 2023). "Thereby, at different E/T ratios and with both, MDA-MB-453 breast carcinoma cells that highly overexpress ErbB2 and MZ-Mel-2 melanoma cells with more moderate ErbB2 expression as targets, comparable cell killing activity of the UniCAR-NK/TM combination and regular CAR-NK cells was found." (PMID 36688995, 2023). "Also, α6β4 integrin signaling promotes resistance to anti-ErbB2 therapy in a mouse model of ErbB2-induced mammary carcinoma." (PMID 38136623, 2023). "The objective of this model-based analysis was to estimate the potential cost-effectiveness of margetuximab compared to trastuzumab, each combined with chemotherapy, for patients with pretreated ERBB2-positive advanced breast cancer in developed and developing countries, like the US and China." (PMID 36159262, 2022). "Genome sequencing efforts have recently identified recurrent somatic mutations in the HER2 (ERBB2) gene in HER2-negative (non-amplified) breast cancer." (PMID 36627899, 2022). "In this study, we used real-world clinical data and gene expression datasets (ERBB2, ESR1, PGR) to provide examples of how g3mclass may help overcome the problems of over-/underdiagnosis and equivocal results in diagnostic tests for breast cancer." (PMID 36335194, 2022). "It has been reported for ERBB2, another therapeutic target of ADC-based therapies, that higher intra-tumoral heterogeneity found by ERBB2-FISH in ERBB2-positive breast cancer patients treated by an anti-ERBB2 therapy, correlated with worse outcome compared to those without ERBB2 heterogeneity." (PMID 35484425, 2022). "On the contrary, in estrogen receptor (ER) and erbB2-positive breast cancer cells, which may have better prognosis, lactadherin exhibits tumor suppressive functions, and is not regulated by p63." (PMID 35409215, 2022). "Second, ERBB3 heterodimerization with ERBB2 has been demonstrated to drive oncogenic signaling in breast cancer as the effects of ERBB2 inhibition could be reversed by increasing ERBB3 phosphorylation and activity to drive a TKI resistance phenotype." (PMID 34675407, 2022). "Moreover, a recent study in breast cancer reported DDR1 to be an interacting partner of ERBB2, and upregulation of DDR1 is one of the compensatory survival mechanisms in lapatinib-resistant tumors." (PMID 35664781, 2022). "Furthermore, depletion of PTPRO from ERBB2-positive breast cancer cells SKBR3 and BT474 also reduced their lapatinib sensitivity." (PMID 35431974, 2022). "In this study, we investigated the potential role of NRG1/ERBB3/ERBB2 signaling in different clinical and molecular subtypes of breast cancers, by combining metanalysis on patients’ survival and gene expression, and by exploring in vitro potential effects induced by the activation of this pathway." (PMID 35406375, 2022). "Indeed, we observed that a small molecule proteasome inhibitor bortezomib used for multiple myeloma treatment upregulates both IRF6 and its target BLNK in ErbB2-positive breast cancer cells BT474." (PMID 35933456, 2022). "Prolactin in breast cancer cells could induce the phosphorylation of ERBB2/HER2, which in turn activates the downstream RAS/MEK/ERK pathway, leading to the proliferation of breast cancer." (PMID 36605402, 2022).
breast cancer (continued). "Similarly, a total of 68 breast cancer patients with ErbB2 amplification were identified, of which 14 had a HER2 FISH ratio > 2.2 and 47 had a HER immunohistochemistry (IHC) score of 3+ or higher." (PMID 35740092, 2022). "Collectively, our data in HER2+ breast cancer cells highlight that NRG1 may exert both pro- and anti-proliferative effects, and may reduce the efficacy of anti-HER2 agents, whereas NRG4 may boost the anti-proliferative effects of anti-ERBB2 agents." (PMID 35664762, 2022). "This nonrandomized clinical trial aims to determine whether neoadjuvant atezolizumab, docetaxel, trastuzumab, and pertuzumab therapy for ERBB2-positive early breast cancer warrants continuation to the next phase." (PMID 35797012, 2022). "This study indicated a substantial role for NBCn1 in ErbB2/HER2-positive breast cancers." (PMID 36145304, 2022). "Indeed, recent functional findings have demonstrated miR-1296-5p involvement in the regulation of breast cancer cell progression by targeting the ERBB2/mTORC1 signaling pathway and tumor suppressor roles in triple-negative breast cancer." (PMID 35740327, 2022). "However, lapatinib has been shown to improve progression-free survival (PFS) in patients with advanced/metastatic ERBB2-positive breast cancer." (PMID 35431974, 2022). "As most erb‐b2 receptor tyrosine kinase 2 (HER2)‐positive breast cancer (BC) patients currently receive dual HER2‐targeting added to neoadjuvant chemotherapy, improved methods for identifying individual response, and assisting postsurgical salvage therapy, are needed." (PMID 34816585, 2022). "Moreover, lapatinib is also approved for patients with ERBB2-positive advanced-stage breast cancer, and can show synergistic activity when used in combination with anti-ERBB2 antibodies such as trastuzumab." (PMID 35431974, 2022). "In addition to ER and PR, receptor tyrosine-protein kinase erbB-2 (HER2) plays a crucial role in breast cancer progression." (PMID 35712498, 2022). "Increased glycolytic activity is also explained by the greater activity of some of the enzymes in the pathway, such as hexokinase 2, which is overexpressed in breast cancer and whose inhibition in transgenic mice that develop breast cancer after overexpression of ErbB2/Neu delays tumor development." (PMID 35053485, 2022). "Moreover, in BALB/C nude mice bearing ErbB2 positive breast cancer, the oral administration of black rice anthocyanins (150 mg/kg/day) decreased transplanted tumor development, hindered pulmonary metastasis, and reduced lung tumor nodules." (PMID 36080219, 2022). "Based on the SOPHIA phase three randomized open-label trial, margetuximab plus chemotherapy had acceptable safety and significant clinical benefits compared with trastuzumab plus chemotherapy in ERBB2-positive advance breast cancer after two or more prior anti-ERBB2 therapies." (PMID 36159262, 2022). "In the current study, we showed that low expression of PTPRO is associated with poor prognosis and PTPRO could serve as an independent prognostic factor for relapse-free survival for patients with ERBB2-enriched breast cancer." (PMID 35431974, 2022). "Moreover, a mutually exclusive or co-occurring connection between FOXPs or between FOXPs and BRCA or ERBB2 was different, suggesting that these gene play an different role in development of breast cancer." (PMID 35614183, 2022). "Indeed, in tamoxifen-resistant (TAMR) estrogen receptor-positive (ER+) breast cancer cells, HuR stabilizes ERBB2 mRNA, while miR-26a/b inhibits its translation." (PMID 35884580, 2022). "However, the relative enrichment of somatic SVs at the same site in ERBB2 (3 out of 19 independent patients) suggests that this is an interest area in breast cancer and needs further validation with more samples." (PMID 35493102, 2022). "For example, ERBB2 (HER2) gene amplification is a molecular target in breast cancer therapy." (PMID 35955591, 2022).
breast cancer (continued). "In breast cancer, ErbB2 amplification/overexpression allows for the effective targeting of ErbB2." (PMID 36230550, 2022). "Before the development of targeted therapies, overexpression of ERBB2 was a negative prognostic marker, but more recently it has been linked to increased pCR rates to neoadjuvant chemotherapy in breast cancer." (PMID 36376989, 2022). "Epidermal growth factor receptor 2 (ERBB2), a well-known oncogene of multiple cancers, such as breast cancer and ovarian cancer, was found to be firmly connected with cancer occurrence, proliferation, metastasis, drug resistance, immune escape and poor prognosis." (PMID 36437939, 2022). "Furthermore, we used publicly available data on mRNA levels in multiple breast cancers to demonstrate that increased BLNK mRNA levels correlate with increased relapse-free survival in a cohort of approximately 400 patients with ErbB2-positive breast cancer." (PMID 35933456, 2022). "As expected, cancer-related pathways in each model were downregulated by treatment; e.g. Kras was downregulated by aCD40 + aPD-1 in the MT4 model, and Erbb2 (Her2) was downregulated in the NDL breast cancer model with both the ablation + aPD-1 and aCD40 + aPD-1 treatments." (PMID 36451859, 2022). "In addition, multiple important breast cancer genes were detected in the epigenetic subnetworks, like gene ERBB2 in subnetwork 19, a known proto-oncogene, that encodes HER2, a member of the human epidermal growth factor receptor." (PMID 36418365, 2022). "Lapatinib is a quinazoline derivative used in the treatment of ErbB2-overexpressing breast cancer." (PMID 36009762, 2022). "This approach could serve for enhancing the anti-tumor effect of ErbB2-targeted therapeutic agents or for treatment of breast cancers resistant to these drugs." (PMID 35933456, 2022). "HER2/ERBB2 is overexpressed in 20–30% of breast cancer cases." (PMID 35281802, 2022). "However, since the unsettled optimal treatment paradigm in later lines, margetuximab provides a promising opportunity for patients with pretreated ERBB2-positive advanced breast cancer, especially for those considering the best supportive care." (PMID 36159262, 2022). "Although cyclin D1 knockout mice were shown to be resistant to the formation of Erbb2 or Ras oncogene-induced breast cancers, cyclin D1 deficiency has not been shown to be protective against tumor formation induced by c-Myc or Wnt-1." (PMID 36017236, 2022). "P-Rex1 is also overexpressed in luminal breast cancer, correlated with oestrogen receptor and ErbB2 expression, and as an effector of ErbB may be particularly important in ErbB2-positive breast cancer." (PMID 36342857, 2022). "Moreover, the epidermal growth factor/Erb-B2 receptor tyrosine kinase 2 (EGF/ERBB2) signaling pathway in breast cancer cells modulated the transcription activity of ESRRA, which was associated with poor prognosis in breast and ovarian cancers." (PMID 36517562, 2022). "If high BMI increases genomic risk in ER-positive, ERBB2-negative breast cancer, weight control will become more important." (PMID 36441548, 2022). "Alterations in P62 may be therapeutic specific, such that chemotherapy-induced autophagy increases LC3-II without altering P62, whereas radiation-induced autophagy increases LC3-II and reduces P62 in murine breast cancer cells overexpressing ERBB2/her2." (PMID 36523497, 2022). "Although ErbB2 is commonly described in breast tumors, a growing number of studies are starting to highlight the valuable role of this molecule as a biomarker in non-breast cancers." (PMID 35448172, 2022).